CAV1 (caveolin 1)
Diseases named in the same sentence as CAV1 in open-access papers (continued):
Sharing a sentence is not in itself a finding about the gene and the disease.
breast carcinoma (continued). "Provided the association between higher CAV1 and BRCA1 deficiency or basal phenotype, that are both risk factors for contralateral breast cancer, cytoplasmic CAV1 may be a proxy marker for these factors, representing a tumor phenotype that tends to occur in the contralateral breast." (PMID 35660849, 2022). "Furthermore, by using a mouse model of genetically induced breast cancer, the reduced expression of CAV-1, associated with elevated SOD-2 and enhanced AMPK activation, was also confirmed in tissue sections from mammary tumors but not in their healthy counterparts." (PMID 33805996, 2021). "Thus, we are curious to know whether autophagy is induced and plays a pro-survival function in those CAV1-deficient breast cancer cells." (PMID 34786475, 2021). "Interestingly, in this context, the loss of CAV1 expression in breast cancer tumor–stroma reportedly induces HIF1α activation and the loss of CAV1 in stromal cells leads to a glycolytic and catabolic phenotype through HIF1α stabilization, favoring synergy with oxidative breast cancer cells." (PMID 32825247, 2020). "In human scirrhous breast cancers, caveolin-1 mutation may activate cell invasiveness." (PMID 32676485, 2020). "Similarly, two independent studies reported that Cav-1 knockout in mammary-tumor-prone mice was associated with an accelerated onset of mammary tumors, with increased multiplicity and tumor burden in the transgenic mammary-tumor-prone mice, but not in wild type mice." (PMID 32528105, 2020). "Caveolin-1, when expressed by fibroblasts, appears to negatively regulate tumour cell growth and the loss of expression is strongly correlated with reduced overall survival, tamoxifen resistance and metastasis in breast cancer and high Gleason score in prostate cancer." (PMID 29416729, 2018). "Importantly, the prognostic value of stromal Cav-1 loss in breast cancers has now been independently validated and has been extended to multiple types of human cancers, such as colorectal cancer, advanced prostate cancer, metastatic melanoma, gastric cancer, and osteosarcoma." (PMID 28546853, 2017). "For example, loss of Cav-1 in cancer-associated fibroblasts (CAFs) could result in an activated tumor microenvironment, thereby driving early tumor recurrence, metastasis, and poor clinical outcomes in breast cancer." (PMID 28546853, 2017). "Furthermore, Cav-1 gene amplification and mutation were reported in a subgroup of breast cancers." (PMID 29141593, 2017). "In addition, Cav-1 is also negatively associated with breast cancer cells' transformation." (PMID 28546853, 2017). "Caveolin-1(CAV-1) was demonstrated to be a tumor suppressor gene and be implicated in the development of breast cancer (BC)." (PMID 29207674, 2017). "Thus, clarifying the underlying roles of Cav-1 in the cytoskeletal reorganization and cell polarity may provide more evidence for breast cancer malignant behaviors." (PMID 26919102, 2016). "Additionally, the loss of Cav1 combined with MMTV-PyMT leads to the acceleration of mammary tumors." (PMID 28018857, 2016). "In addition, several studies suggest that stromal Cav-1 loss is an independent factor associated with poor clinical prognosis of breast cancer patients, indicating that stromal Cav-1 loss may assist cancer metastasis or drug resistance." (PMID 26431273, 2015). "With respect to breast cancer caveolin-1 has been observed in both tumor cells and stromal cells surrounding tumors however most of the recent research has focused on how the loss of caveolin-1 in the stromal cells surrounding the tumor alters the tumor microenvironment." (PMID 22356861, 2012). "Interestingly, pockets of caveolin-1 positive cells could be observed in some of the IGF-IR-induced mammary tumors and these caveolin-1 positive cells were associated with tumor cells that expressed basal cytokeratins (cytokeratins 5 and 14)." (PMID 22356861, 2012).
breast carcinoma (continued). "Additionally, a mutation in Cav-1 at codon 132 (P132L) was found in 16% of the primary human breast cancer cases, and interbreeding Cav1−/− mice with MMTVPyMT mice (mouse mammary tumor virus-Polyoma middle T antigen) accelerated onset of mammary tumors in their offspring." (PMID 20700465, 2010). "This study detected the expression of CAV-1 in 300 cases of invasive breast cancer paraffin tissues through IHC, and analyzed the relationship between CAV-1 expression and the clinicopathological characteristics and prognosis of breast cancer patients." (PMID 42063698, 2026). "Currently, there are few studies exploring the expression of Caveolin-1 (CAV-1) in breast cancer tissues and its clinicopathological significance using immunohistochemistry (IHC) technology." (PMID 42063698, 2026). "Cav-1 in breast cancer-derived EXOs can act as a signaling molecule, regulating the formation of PMN in lung epithelial cells and inhibiting the PTEN/CCL2/VEGF-A signaling pathway in lung macrophages, thus promoting their M2 polarization and angiogenesis." (PMID 40486870, 2025). "Breast cancer cell-derived caveolin-1 (CAV1)-positive exosomes, enriched with integrin α6β4 on their surface, activate lung neutrophils via the TLR4-NF-κB pathway, driving their polarization into the N2 phenotype." (PMID 40564894, 2025). "Knockdown of Cav1 by siRNA in a human breast cancer cell line promoted its proliferation and invasiveness by enhancing the activity of large-conductance Ca2+-activated potassium channels." (PMID 41439026, 2025). "Recent findings indicate that Cav-1 acts as a critical regulator of late-stage breast cancer metastasis, with its phosphorylation state playing a pivotal role." (PMID 40358155, 2025). "In breast cancer, Cav-1 expression is downregulated in CAFs and correlates positively with patient prognosis, though some studies suggest the opposite." (PMID 40230452, 2025). "In breast cancer, Cav-1 expression can range from high to low, yet observations in the literature are contradictory." (PMID 40579643, 2025). "This regulatory dichotomy extends beyond hepatic systems, as evidenced by breast cancer studies showing that macrophage migration inhibitory factor (MIF)-mediated Cav-1 phosphorylation modulates CD11b+ immune cell recruitment." (PMID 40430042, 2025). "In breast cancer cells, phosphorylated Cav-1 interacts with Mitofusin 2 (Mfn2) and Dynamin related protein 1 (Drp1), keeping them away from mitochondria, thereby reducing mitophagy." (PMID 41030451, 2025). "Conversely, upregulation of Cav-1 protein suppressed the proliferation and invasion of breast cancer cells." (PMID 41439026, 2025). "Cav-1 knockout in these cells suppressed lung metastasis in a syngeneic mouse model, providing the first in vivo evidence of the role of Cav-1 in regulating the migration capacity of breast cancer cells." (PMID 41439026, 2025). "Autophagy enhancement and downregulation of Cav-1 expression have been observed in human breast cancer cell lines and cancer tissues, and these two changes were mutually regulated." (PMID 41030451, 2025). "Cav‐1 also serves as a negative regulator of pro‐proliferative and oncogenic proteins, including those involved in breast cancer, a common malignancy in SSc patients." (PMID 40778471, 2025). "EXOs play a key role in the transport of Cav-1 between the microenvironments of primary breast cancer and metastatic organs." (PMID 40486870, 2025). "CAV1 has been shown to modulate the treatment efficacy of chemotherapy (including anthracyclines and taxanes) in breast cancer in both preclinical and clinical settings." (PMID 38959243, 2024). "Here, we present the first evidence that Cav-1 knockout in mammary epithelial cells significantly reduces lung metastasis in syngeneic breast cancer mouse models." (PMID 39244591, 2024). "CAV1 has been shown to modulate treatment efficacy of chemotherapy (including epirubicin and taxanes) and trastuzumab in breast cancer and other cancers." (PMID 38509243, 2024).
breast carcinoma (continued). "The consistent correlation across cohorts with the lipid module indicates a connection between CAV1 and lipid metabolism in breast cancer, which is in line with other studies." (PMID 38959243, 2024). "Specifically in BC, CAV-1 expression is associated with worse disease free survival and overall survival in human breast cancer patients, and CAV-1 in EVs promoted breast cancer invasiveness in a murine model with MDA-MD-231 cells." (PMID 38969706, 2024). "The previous study has shown that Cav-1 is involved in low shear stress-induced breast cell motility, FAs dynamics and adhesion of breast cancer cells." (PMID 39318372, 2024). "Under low shear stress conditions (2 dyn/cm2), MDA-MB-231 cells, a human breast carcinoma cell line, developed resistance to anoikis, characterized by increased Cav-1 protein expression." (PMID 38544822, 2024). "Cav-1 is recognized as a tumor promoter in breast cancer, although its role in cancer is context-dependent and governs cancer cell metabolism through diverse molecular pathways." (PMID 38544822, 2024). "Researchers discovered that the polarization of pulmonary macrophages by Caveolin-1 transported by exosomes could be inextricably linked to pre-metastatic microenvironment creation before breast cancer (BC) cells metastasize to the lung." (PMID 38195554, 2024). "Later, some scholars designed experiments to force the re-expression of Cav-1 in transformed breast cancer cells, which not only eliminated the cancerous potential of these cells but also inhibited aggressiveness." (PMID 37828916, 2023). "Studies have shown that abnormal expression of Cav-1 can enhance EGFR signaling and increase the malignant potential of MCF-7 breast cancer cells, while overexpression of Cav-1 can enhance the cell growth inhibition ability of EGFR tyrosine kinase inhibitors." (PMID 37828916, 2023). "The knockdown of CAV1 leads to increased expression of aromatase in adipocytes, increasing the free estrogen in the surrounding tissues promoting breast cancer tumorigenesis." (PMID 37017811, 2023). "In breast cancer samples, the high expression levels of stromal PKM2 were concomitantly seen with a loss of stromal caveolin-1, an event typically associated with the reverse Warburg effect." (PMID 36765947, 2023). "In breast cancer, the downregulation of Cav-1 expression in CAFs has been observed, and its expression is positively associated with patient prognosis." (PMID 38273859, 2023). "In a co-culture system of breast cancer cells and CAFs, adjacent CAFs can induce oxidative stress, which promotes cancer progression by reducing the levels of stromal Cav-1 and increasing the expression of autophagy markers." (PMID 38067169, 2023). "Gene expression profile analysis showed that the expression level of Cav-1 in bone marrow metastatic breast cancer cells was significantly higher than that in CTCs." (PMID 37828916, 2023). "Regarding to the role of CAV1 in drug resistance, CAV1 has been found to be upregulated in drug-resistant colon cancer, breast cancer and lung cancers." (PMID 37642765, 2023). "Breast cancer patients with high or high expression of Cav-1 in stromal cells had higher overall survival and disease-free survival than patients with no or low expression of Cav-1." (PMID 37828916, 2023). "Firstly, abnormal expression of caveolin-1 has been found in several types of malignant tumors, such as gastric cancer, breast cancer, lung cancer, and prostate cancer." (PMID 37576808, 2023). "In recent years, the role of Cav-1 in negatively regulating the proliferation of breast cancer by inhibiting autophagy has been widely studied." (PMID 37828916, 2023). "In summary, these data support a novel microRNA-mediated mechanism of Cav1 reduction in breast cancer patients and warrants future studies exploring it role in promoting breast cancer disparities." (PMID 37822942, 2023).
breast carcinoma (continued). "Enhanced phosphorylation on Y14 of CAV1 increases focal adhesion turnover, activation of Rac-1, and migration/invasion in metastatic melanoma, as well as breast cancer cells." (PMID 38069269, 2023). "Other studies have shown that downregulation of Cav-1 in breast cancer MCF-7 cells can increase the expression of large conductive Ca2+-activated potassium channels (BKCa) in the cell membrane and promote cell proliferation." (PMID 37828916, 2023). "A recent study found that CAV1 activation drives mitochondrial fission and cytoskeleton remodeling to promote breast cancer migration." (PMID 37642765, 2023). "Studies have shown that the interstitium of breast cancer cells is usually in a high-oxygen microenvironment, and the transport efficiency of Cav-1 into cells is low." (PMID 37828916, 2023). "At present, the findings of most studies suggest that Cav-1 can inhibit the proliferation of breast cancer and act as a tumor suppressor in the occurrence and development of breast cancer." (PMID 37828916, 2023). "We previously reported that tumor-specific Caveolin-1 (CAV1) was prognostic for both contralateral breast cancer (CAV1 in malignant cells) and locoregional recurrence (CAV1 in stromal cells)." (PMID 37017811, 2023). "We previously reported that tumor-specific CAV1 was a predictor for both contralateral breast cancer and locoregional recurrence depending on its localization." (PMID 37017811, 2023). "Cav-1 knockdown in fibroblasts appears to protect breast cancer cell death in co-culture, thus indicating another mechanism through which CAFs can promote cancer cell survival." (PMID 38067169, 2023). "CAV1 promotes tumor invasion and cancer cell migration in gastric cancer, lung cancer, renal and breast cancers." (PMID 37642765, 2023). "EHD2 and Caveolin-1/2 are co-overexpressed in breast cancers and EHD2 regulates cell surface caveolae." (PMID 36625722, 2023). "It is concluded that Cav-1 can affect cell proliferation in breast cancer by inducing changes in receptor activity and membrane surface ion channels, regulating the cell cycle, and regulating the tumor microenvironment (TME) and intercellular interactions." (PMID 37828916, 2023). "Another study has found that Caveolin-1 is upregulated in metastatic breast cancer cell-secreted EVs and fosters breast cancer invasion and metastasis through the adhesion proteins." (PMID 37534210, 2023). "Other researchers support the second view, and their evidence is that the Cav-1 gene locus is located at the aggregation point of suppressor genes in many human epithelial origin malignancies, including breast cancer." (PMID 37828916, 2023). "It would, therefore, be of interest to further elucidate the role of CAV1 in breast cancer by studying CAV1 genotypes." (PMID 37017811, 2023). "We next investigated the consequence of CAV1 silencing on the ability of breast cancer cell spheroids to invade a 3D collagen matrix environment." (PMID 37903910, 2023). "(C) Immunoblot analysis of coordinate EHD2 and CAV1 expression in immortal mammary epithelial cells and breast cancer cell lines." (PMID 36625722, 2023). "Cav-1 is highly expressed in T-DM1-resistant HER-2 (+) breast cancer cells, and T-DM1 fuses with lysosomes intracellularly through Caveolae-mediated endocytosis, while the acidic environment in the lysosomal Cavity weakens the drug efficacy of T-DM1." (PMID 37828916, 2023). "Cavin-1 inhibits Cav-1-induced cell membrane tubule formation, and its specific role in breast cancer remains controversial." (PMID 37828916, 2023). "Low shear stress increases the motility of breast cancer cells via CAV1-FAK and CAV1-ROCK signaling." (PMID 37864030, 2023). "At present, the role of Cav-1 in breast cancer apoptosis is still controversial, and there are different studies on its ability to promote or inhibit apoptosis." (PMID 37828916, 2023).
breast carcinoma (continued). "In breast cancer, Cav-1 deletion from CAFs is related to a more advanced tumor stage, early cancer recurrence, lymph node metastasis, and poor prognosis." (PMID 37143134, 2023). "At present, the effect of Cav-1 on the apoptosis of breast cancer cells is mainly dependent on apoptosis-related proteins and autophagy." (PMID 37828916, 2023). "According to the data from GEPIA, the CAV-1 expression level in breast cancer tissues was significantly lower than that in normal tissues (P<0.05)." (PMID 36604141, 2022). "Conversely, in a separate study, breast-cancer cells were found to internalize T-DM1 into intracellular CAV1-positive puncta and alter their trafficking to the lysosome." (PMID 35158857, 2022). "Some previous investigations indicated that CAV-1 expression in CAFs has a positive relationship with a better prognosis of breast cancer patients." (PMID 36604141, 2022). "On the contrary, siRNA-mediated knockdown of CAV1 decreased the sensitivity of breast cancer cells to T-DM1." (PMID 35158857, 2022). "It has been reported that CAV1 plays a key role in breast cancer cell proliferation, apoptosis, autophagy, invasion, migration, and breast cancer metastasis." (PMID 36233075, 2022). "The expression of CAVIN1 is upregulated in an adriamycin-resistant breast-cancer cell line along with the expression of P-gp, CAV1, and CAVIN2." (PMID 35158857, 2022). "Among those, attention has been given to the essential role of CAV-1 in the occurrence and progression of breast cancer and as a potential therapeutic target." (PMID 36604141, 2022). "It is only that the expression level of CAV1 is regulated by other factors, and it plays a dual role in inhibition or promotion in the process of breast cancer." (PMID 36233075, 2022). "A wound-healing assay was performed before and after treatment with NS1643 for 24 h in MDA-MB-231 breast cancer cells treated with control or Cav1-specific shRNA." (PMID 35954304, 2022). "In a recent study in breast-cancer stem cells, it was reported that chemotherapy enhanced the expression of CAV1 expression in vitro and in vivo, and this was accompanied by co-overexpression of β-catenin and ATP-binding cassette subfamily G member 2 (ABCG2)." (PMID 35158857, 2022). "We establish a specific small interfering RNA (siRNA) to inhibit CAV-1 expression in fibroblasts and coculture them with BCCs to investigate the effect of CAV‐1-deficient fibroblasts and the tumor microenvironment on breast cancer progression." (PMID 36604141, 2022). "Then, a large amount of miR-203 is expressed, which, in turn, blocks the production of a large amount of CAV1, thereby successfully inhibiting the progression of breast cancer cells." (PMID 36233075, 2022). "In the study of mechanisms in breast cancer, CAV1 has been our target, and we strive to identify the key molecules that act on it." (PMID 36233075, 2022). "Caveolin-1 (Cav-1) is a structural membrane and scaffolding protein shown to be a key regulator of late-stage breast cancer metastasis." (PMID 35954304, 2022). "In breast cancer, CAV1 interacts with both HER2 and ER, suggesting that CAV1 plays different roles depending on receptor expression and localization." (PMID 35660849, 2022). "In breast cancer, overexpression of CAV1 in a doxorubicin-resistant breast cancer cell line (low CAV1 and high P-gp) resulted in downregulation of P-gp." (PMID 35158857, 2022). "The expression levels of Cav-1 and β-catenin were found to be highly correlated in breast cancer cells after exposure to chemotherapy, both in vitro and in vivo." (PMID 35954304, 2022). "We found CAV1 in TCGA and GOBO to be associated with basal subtype, EMT, EGFR expression, and BRCAness, in line with others, all common in ER– breast cancer." (PMID 35660849, 2022).